NLRP3 (NLR family pyrin domain containing 3)
Diseases named in the same sentence as NLRP3 in open-access papers (continued):
Sharing a sentence is not in itself a finding about the gene and the disease.
tuberculosis (24 papers, 2011 to 2025). A chronic, recurrent infection caused by the bacterium Mycobacterium tuberculosis. "The existence of a small molecule inhibitor (MCC950), which targets the NLRP3 inflammasome, suggests more effective ways to both prevent and treat the inflammatory symptoms of tuberculosis-associated IRIS and should be explored in future studies." (PMID 27932622, 2017). "Our aim was to investigate the association between polymorphisms in CARD8 and NLRP3 and active tuberculosis (TB) as well as their relationship to treatment outcome in a high-endemic setting for TB." (PMID 30816317, 2019). "However, activation of the NLRP3 inflammasome by M. tuberculosis is uncoupled from susceptibility to active TB." (PMID 36255321, 2022). "By intervening the NLRP3 inflammasome pathway, it can significantly reduce the inflammatory response and mortality of microglia during the tuberculosis H37Ra strain infection." (PMID 33928044, 2021). "Overall, our findings point to PM damage as a shared mechanism for this group of NLRP3 activators, extending the relevance beyond tuberculosis disease." (PMID 32385301, 2020). "NO (nitric oxide) which is increased during Mtb infection has the capacity to negatively regulate the NLRP3 inflammasome so that it can suppress tissue damage produced by continues activation of innate immunity and control the immunopathology of tuberculosis." (PMID 27366746, 2016). "Therefore, in this study, we used a co-culture model of rat microglia and tuberculosis H37Ra strain to explore the influence of tuberculosis infection on the NLRP3 inflammasome in microglia and its regulation mechanism." (PMID 33928044, 2021). "Thus, further studies in relevant in vivo systems will be necessary to clarify the prevalence and importance of NLRP3 activation and the pyroptotic pathway during different stages of tuberculosis disease." (PMID 32385301, 2020). "Notably, higher levels of IL-1β and NLRP3 mRNA were observed in monocyte-derived macrophage from active tuberculosis patients as compared with healthy subjects, suggesting the involvement of NLRP3 inflammasome in human response to mycobacterial infection." (PMID 22558425, 2012). "Because macrophage necrotic death is central to tuberculosis pathogenesis, targeting NLRP3 to block macrophage necrotic death may represent an attractive therapeutic approach." (PMID 21740493, 2011). "In particular, low miR-20b-5p expression and activated NLRP3/caspase-1/IL-1β pathway were observed in a TB mouse model stably infected with M. tuberculosis." (PMID 32987746, 2020). "While ouabain monotherapy significantly reduced inflammation, the incomplete normalization of NLRP3/IL-1β levels suggests two complementary strategies: Low-dose corticosteroids could augment ouabain’s immunomodulation while minimizing toxicity, as shown in tuberculosis models." (PMID 40895521, 2025). "In this context, we have focus on one SNV in the AIM2 inflammasome in tuberculosis together with two other SNVs, one in CARD8 and one in CTSB, that are related to NLRP3 pathway." (PMID 33868225, 2021). "Their mechanism of action involves NLRP3 inflammasome activation, dendritic cell recruitment, and cytokine production (IFN-γ, IL-1β) and can be particularly valuable for adjuvant vaccines to diseases requiring strong cellular immunity (e.g., malaria, tuberculosis, HIV)." (PMID 40870989, 2025). "Furthermore, an interesting observation is that functional P2X7Rs canmediate the activation of NLRP3 inflammasomes, whereas non-functional receptorsexhibit a higher expression frequency in patients with TAK combined withpulmonary tuberculosis." (PMID 41209134, 2025).
cystic fibrosis (23 papers, 2017 to 2026). Autosomal recessive disorder caused by pathogenic variants in the CFTR gene (cystic fibrosis transmembrane conductance regulator), which encodes a chloride and bicarbonate channel expressed in epithelial cells, and follow the diagnosis criteria. "In recent years, the NLRP3 inflammasome has also been implicated in inflammation that characterizes cystic fibrosis." (PMID 37895314, 2023). "In this regard, QS-defective mutants are implicated in the dysregulation of NLRP3 inflammasome activation that accounts for the severe pathology of cystic fibrosis." (PMID 28396663, 2017). "Several previous reports suggested that inhibition of the NLRP3 inflammasome attenuates cystic fibrosis, colonic inflammation, and other inflammatory disorders." (PMID 35720309, 2022). "Several lines of evidence also confirmed that NLRC4-derived IL-1Ra controlled NLRP3 activation by the ubiquitin/proteasomal degradation pathway in cystic fibrosis." (PMID 29692782, 2018). "Recent studies have further revealed that NETs activate NLRP3 inflammasomes in airway epithelial cells, amplifying inflammatory cascades, and that NETs‐derived proteases directly impair epithelial barrier integrity in cystic fibrosis." (PMID 41506246, 2026). "Notably, previous studies revealed that higher MCU activity triggers NLRP3 inflammasome activation contributing to inflammation and cystic fibrosis." (PMID 39523398, 2024). "NLRP3 inflammasomes responses to many types of pyogenic bacterial infection and plays important roles in different infectious disease such as respiratory infection, cystic fibrosis and keratitis." (PMID 36068223, 2022). "As an example, chronic stresses capable of increasing mitochondrial Ca2+ entry induce sustained inflammation, and MCU-mediated Ca2+ overload is essential for triggering NLRP3-mediated inflammation in patients with cystic fibrosis during infection with Pseudomonas aeruginosa." (PMID 32182899, 2020). "On the other hand, NLRP3 defects have also been associated with a better prognosis in aspergillosis associated with cystic fibrosis, and these defects had no impact in chromoblastomycosis." (PMID 33380899, 2020). "Indeed, previous studies have demonstrated NLRP3 inflammasome activation in response to Pseudomonas infection in human bronchial epithelial cells derived from cystic fibrosis patients." (PMID 30062052, 2018). "In 2020, Rimessi’s group demonstrated that the inflammatory response in cystic fibrosis is related to overactivation of the NLRP3 inflammasome." (PMID 38069047, 2023). "However, it is intriguing to speculate that a persistent mitochondrial unfolded protein response (UPRmt) may be involved in this phenomenon and NLRP3 inflammasome activation bronchial cells in cystic fibrosis." (PMID 33850310, 2021). "In addition, it has been demonstrated that mitochondrial Ca2+ accumulation regulates NLRP3 activation in epithelial cells of cystic fibrosis inflammatory lung disease." (PMID 38069047, 2023). "In cystic fibrosis, P. aeruginosa infection in bronchial cells from cystic fibrosis patients enhanced VAPB-PTPIP51 tethering at MAMs, disrupting autophagy and increasing mitochondrial Ca2+ uptake, which triggers NLRP3 inflammasome activation and hyperinflammation." (PMID 41367495, 2025). "Additionally, whether pyroptosis participates in cystic fibrosis and sarcoidosis or not is largely unknown, though the activation of NLRP3 inflammasome is found in CF and sarcoidosis." (PMID 35819638, 2022).
glioblastoma (23 papers, 2014 to 2025). The most malignant astrocytic tumor (WHO grade IV). "It was also observed that miR-214 inhibits the caspase-1 and NLRP3 expression resulting in the suppression of tumor growth and migration in glioblastoma." (PMID 38421496, 2024). "A combination therapy for glioblastoma should also target the NLRP3 inflammasome pathway, which induces tumor metastasis in response to S1P/S1PR1 and C3 complement signaling." (PMID 38894892, 2024). "The NLRP3 downstream effectors, IL-1β and NF-κB, are abundantly present in the tumor microenvironment of glioblastomas, contributing to their development." (PMID 38461458, 2024). "miR-223 was found to be less in glioblastoma and overexpression of miR-223 arrested NLRP3 inflammasome contributing to the repression of cell proliferation and migration." (PMID 38421496, 2024). "On the other hand, some studies reported that NLRP3 inhibition reduced tumor growth and prolonged the survival rate in a mouse model of glioblastoma." (PMID 38347045, 2024). "In glioblastoma, the post-transcriptional regulators of NLRP3 such as miR-22 and miR-30e are reported to be under-expressed." (PMID 38421496, 2024). "ZIKV infection induced the activation of NLR family pyrin domain containing 3 (NLRP3) inflammasome in glioblastoma cells." (PMID 37946006, 2024). "After the shKDELC2 transfection of the glioblastoma cells, there was a significant decrease in NLRP3, caspase-1, and IL-1β expression compared to the shLuc-transfected GBM8401 and U87 cells." (PMID 37107298, 2023). "In the studies, EV71 infection, ERK1/2 phosphorylation, and activation of NLRP3 are abolished in glioblastoma cells with low vimentin expression by CRISPR/Cas9-mediated knockdown." (PMID 35807435, 2022). "Upon LPS/Nigericin treatment, activation of NLRP3 was the highest in prostate cancer and glioblastoma cells, whilst it was the lowest in the neuroblastoma cell line, SH-SY5Y." (PMID 33613529, 2020). "Glioblastoma IL-1β processing occurred by the NLRP3 inflammasome, and ATP and nigericin increased IL-1β processing by upregulating NLRP3 expression, similar to macrophages." (PMID 25054228, 2014). "Therefore, suppressing NLRP3 expression and inflammation can inhibit glioblastoma’s potential for malignancy." (PMID 38894892, 2024). "In addition, the nucleotide-binding domain leucine-rich family pyrin-containing 3 (NLRP3) inflammasome and autophagy were important in promoting glioblastoma vascularization induced by mitochondrial ROS." (PMID 37107298, 2023). "We concluded that KDELC2 might stimulate glioblastoma angiogenesis by activating the NLRP3 inflammasome and autophagy via mitochondrial ROS generation." (PMID 37107298, 2023). "We hypothesize that the VIM-ERK-NF-κB signaling pathway activation induces NLRP3 inflammasome formation in EV71-infected glioblastoma cells." (PMID 35807435, 2022). "In addition, IP-Se-06 displayed significant inhibition of p38 MAPK and p-p38, leading to inhibition of inflammasome complex proteins (NLRP3 and caspase-1) in glioblastoma cells." (PMID 35360199, 2022). "Therefore, we sought to determine the effect of NLRP3 modulation on the growth of the different types of cancer cells, derived from lung, breast, and prostate cancers as well as neuroblastoma and glioblastoma in-vitro." (PMID 33613529, 2020). "Also, it has been shown that IL-1β is aberrantly expressed in glioblastoma cells as a result of NLRP3 inflammasome activation." (PMID 30447690, 2018). "NLRP3 inflammasome can active in glioblastoma multiforme (GBM) cells constitutively." (PMID 27652274, 2016). "Moreover, by using a mouse glioblastoma model, it has been proved that the inhibition of NLRP3 can reduce tumor growth and prolong the survival of mouse following IR treatment." (PMID 27652274, 2016). "In addition, the NLRP3 inflammasomes are involved in radiotherapy resistance in glioblastoma." (PMID 36457716, 2022).
glioblastoma (continued). "In addition, the inhibition of MEK/ERK 1/2 signaling by IP-Se-06 resulted in antiproliferative activity, as well as in the inhibition of p38 mitogen-activated protein kinase, thereby leading to inhibition of inflammasome complex proteins, such as NLRP3 and caspase-1 in glioblastoma cells." (PMID 35360199, 2022). "High NLRP3 inflammasome activation and high levels of inflammasome products are found in malignant glioblastoma (GBM)." (PMID 31118894, 2019). "This narrative review focuses on adult diffuse gliomas and glioblastoma (GBM) and evaluates how NF-κB, COX-2–PGE2 (EP2/EP4), and NLRP3–IL-1 signaling intersect with natural anti-inflammatory compounds to shape the TME." (PMID 41463173, 2025). "Therefore, our data confirmed KDELC2 could induce an NLRP3 inflammasome in glioblastoma cells." (PMID 37107298, 2023). "Our results revealed that NLRP3 expression significantly decreased in temozolomide, direct helium, and indirect argon CAP-treated groups compared with the baseline levels in the animal model of glioblastoma, which was in line with the increased survival rate in these groups." (PMID 38347045, 2024). "targeted glioblastoma (GBM) using genetically modified Salmonella, whose lysis releases LPS that binds to TLR4 on host cells, activating the NLRP3-Caspase-1-GSDMD pathway and inducing pyroptosis." (PMID 39575419, 2024). "As applying an NLRP3 inhibitor suppressed glioblastoma angiogenesis and overexpressed KDELC2 could reverse the inhibition of tumor vascularity, we demonstrated that KDELC2 played a critical role in enhancing or regulating glioblastoma angiogenesis via ROS-induced NLRP3 activation." (PMID 37107298, 2023).
intervertebral disc degeneration (23 papers, 2017 to 2025). "Intervertebral disc degeneration and pain are associated with the nucleotide-binding domain, leucine-rich repeat, and pyrin domain-containing 3 (NLRP3) inflammasome activation and the processing of interleukin-1 beta (IL-1β)." (PMID 39456246, 2024). "It has been reported that NLRP3 inflammasome activation was modulated by the cGAS‐STING pathway in some diseases including intervertebral disc degeneration and acute liver injury." (PMID 40522023, 2025). "And in another research, MCS-EVs were proven to ameliorate intervertebral disc degeneration through suppressing NLRP3 inflammasome activation in nucleus pulposus cells." (PMID 35387668, 2022). "For instance, Morin mitigates thioredoxin-interacting protein (TXNIP)/NLRP3/Caspase-1 signaling pathway-mediated pyroptosis in nucleus pulposus cells and ameliorates intervertebral disc degeneration." (PMID 34366853, 2021). "In this study, we observed significant activation of the NLRP3 inflammasome in NP tissues obtained from patients with degenerative disc disease compared to that with idiopathic scoliosis according to results detected by Western blot and immunofluorescence." (PMID 28224704, 2017). "The levels of cGAS, STING, and NLRP3 were significantly upregulated in intervertebral disc degeneration (IDD) patients, and epigallocatechin gallate (EGCG) treatment could inhibit cell apoptosis by target cGAS/STING/NLRP3." (PMID 40303074, 2024). "Also, a study revealed that LINC00969 accelerates intervertebral disc degeneration via sponging miR335-3p and controlling NLRP3 inflammasome activation." (PMID 37520321, 2023). "Mitophagy alleviates intervertebral disc degeneration (IVDD) by suppressing cGAS–STING and NLRP3 inflammasome-mediated pyroptosis pathways; however, its metabolic regulatory mechanism remains unexplored." (PMID 41199783, 2025). "A research on intervertebral disc degeneration found that METTL14 specifically induced an increase in the m6A modification of NLRP3 mRNA and increased the expression of NLRP3 protein." (PMID 35141221, 2022). "NLRP3 inflammasome activation was significantly increased in degenerated disc and IDD model, and drugs targeting NLRP3, such as cortistain, melatonin, and mesenchymal stem cell- (MSC-) derived exosomes, ameliorated intervertebral disc degeneration via repressing NLRP3 activation." (PMID 36193061, 2022). "Similarly, MSC-derived exosomes effectively reduced NLRP3 inflammasome to ameliorate intervertebral disc degeneration and protected against hypoxia/reoxygenation-induced pyroptosis of cardiomyocytes through the miRNA-100-5P/FOXO3/NLRP3 pathway." (PMID 34294138, 2021).
Parkinson’s (23 papers, 2018 to 2025). "Dopamine blocks microglial NLRP3 inflammasome activation in the MPTP model, but its effects in this framework, highly relevant to PD, remain unexplored in primary human microglia and in other in vivo parkinsonism models." (PMID 35172843, 2022).
pericarditis (23 papers, 2016 to 2026). An inflammatory process affecting the pericardium. "Eleven variants were located in genes already associated with recurrent pericarditis (NLRP3, TNFRSF1A and MEFV) and five in inflammation/immunodeficiency-related genes (IFIH1, NFKBIA, JAK1, NOD2 and ALPK1)." (PMID 39347728, 2024). "Previous studies showed that IL1β can be activated by the NLRP3 inflammasome, which plays a central role in acute pericarditis clinical manifestations." (PMID 39975900, 2025). "The sharing of MEFV-1 as a common gene between FMF and recurrent pericarditis underscores the importance of the NLRP3 inflammasome in both conditions." (PMID 40564905, 2025). "Mauro and associates were the first to validate the therapeutic impact of blocking the NLRP3 inflammasome in a mouse model of acute pericarditis." (PMID 40079000, 2025). "Compared with those in the controls, the expression levels of NLRP3 and caspase-1 were notably elevated in the pericarditis patients, highlighting the key elements of pericarditis development and confirming the theory of medication." (PMID 40079000, 2025). "The role of NLRP3 inflammasome activation in the development of pericarditis has been confirmed by various researchers." (PMID 40868251, 2025). "The inhibition of IL-1 in mice with pericarditis turned off the NLRP3-mediated inflammation, ameliorating pericardial effusion and thickening." (PMID 41272654, 2025). "It is possible that the beneficial outcome is mediated by the inhibition of NLRP3 inflammasome and IL-1, which have been demonstrated to be highly active in human pericarditis samples." (PMID 39935815, 2025). "In response to damage to pericardial mesothelial cells, local inflammation—pericarditis—develops, which is then exacerbated by NLRP3 inflammasome activation." (PMID 40868251, 2025). "Our rat model of sterile pericarditis extends this paradigm as application of talc increased NLRP3 activation, suggesting that postoperative inflammation exacerbates NLRP3 activation and atrial tissue remodeling." (PMID 38169629, 2024). "The accumulating evidence points toa role for the NLRP3 inflammasome/IL-1β axis in the auto-inflammatoryprocess sustaining recurrent pericarditis, as outlined by a recent work." (PMID 39077487, 2023). "It has been shown that inflammation through the NLRP3 inflammasome pathway is the key to pericarditis pathophysiology." (PMID 37476333, 2023). "In the next future, research should be focused on theselective pharmacological blockade of the NLRP3 inflammasome to addressadditional pathogenetic mechanisms involved in acute and recurrent pericarditis." (PMID 39077487, 2023). "Zymosan A, a yeast-derived activator of the NLRP3, was injected in the pericardial sac of CD-1 male mice to induce the pericarditis model." (PMID 36204568, 2022). "Combined with the positive therapeutic impact of colchicine and anakinra in pericarditis treatment, inhibiting NLRP3 and IL-1 pathway tends to be a promising therapeutic target for acute and recurrent pericarditis." (PMID 36204568, 2022). "This is of particular note in the case of NLRP3 in view of a recent study that showed upregulation of NLRP3 inflammasome activity in the pericardia of patients with recurrent pericarditis complicated by constriction." (PMID 35658515, 2022). "New research has highlighted the role of the NLRP3 inflammasome in the pathophysiology of pericarditis, which may pave the way for new therapies." (PMID 42018907, 2026). "Moreover, the NLRP3 inhibitor showed significant ability to reduce pericardial thickening and pericardial effusion in mice with acute pericarditis." (PMID 41272654, 2025). "Acute and recurrent pericarditis may benefit from blocking the NLRP3 and IL-1 pathways, especially when coupled with the favorable therapeutic effects of colchicine and anakinra." (PMID 40079000, 2025). "It is possible to assume that NLRP3 could play a central role also in radiation-induced pericarditis." (PMID 41272654, 2025).